LINC02015 (long independently transcribed non-coding RNA 2015)
Synonyms: KCCAT211
Gene: Long non-coding RNA gene on chromosome 3 (177,816,847 to 177,940,299, forward strand). Ensembl gene ENSG00000231574.
Diseases named in the same sentence as LINC02015 in open-access papers:
LINC02015 is named in the same sentence as 2 diseases in open-access papers, as found by Europe PMC text mining. Sharing a sentence is not in itself a finding about the gene and the disease. The quoted sentences say what the papers report.
cancer (1 paper, 2021). A tumor composed of atypical neoplastic, often pleomorphic cells that invade other tissues. "It was found that 5 lncRNAs (CATIP-AS2, TTC3-AS1, LINC01993, LINC01564, and LINC02015) were upregulated in various types of cancers including GC." (PMID 34257651, 2021).
tumours (1 paper, 2024). "Numerous lncRNAs and their sponged targets have been identified as both diagnostic and therapeutic targets in the development of GBM tumours, such as LINC02015, H19, KIAA0495, AC068888.1 and MALAT1." (PMID 38594690, 2024).